MAGOHB (mago homolog B, exon junction complex subunit)
Diseases named in the same sentence as MAGOHB in open-access papers:
MAGOHB is named in the same sentence as 16 diseases in open-access papers, as found by Europe PMC text mining. Sharing a sentence is not in itself a finding about the gene and the disease. The quoted sentences say what the papers report.
breast cancer (3 papers, 2017 to 2023). A primary or metastatic malignant neoplasm involving the breast. "The differential gene expression pattern of MAGOHB has been implicated in breast cancer development." (PMID 33670352, 2021). "When the miR-101-5p-associated pathways in breast cancer were assessed using RNA-seq, a particular group of genes, HMGB3, ESRP1, GINS1, TPD52, SRPK1, VANGL1, and MAGOHB, were suggested to be associated with a poor prognosis of BC." (PMID 38132441, 2023).
melanoma (3 papers, 2022 to 2024). A malignant, usually aggressive tumor composed of atypical, neoplastic melanocytes. "The experiment revealed that while a single KD of MAGOH increased the number of apoptotic cells when compared to the siCtrl, this effect was only statistically significant after a combined KD of MAGOH and MAGOHB for the melanoma cell lines Mel Ho and SKMel28." (PMID 36497117, 2022). "To analyze the protein expression of MAGOH and MAGOHB in melanoma, we performed Western blot experiments of several cutaneous melanoma cell lines as well as from normal human epidermal melanocytes (NHEM)." (PMID 36497117, 2022). "We observed an increased MAGOH/MAGOHB protein expression in most melanoma cell lines compared to healthy NHEM." (PMID 36497117, 2022). "Analyzing the occurrence of apoptosis showed that the KD of MAGOH and MAGOHB in melanoma cells using the siMAGOH/B Pool also significantly increased the proportion of apoptotic cells at a similar level compared to the simultaneous KD of MAGOH and MAGOHB with single siRNAs." (PMID 36497117, 2022). "However, for some melanoma cell lines, such as Mel Ho and SKMel28, MAGOHB also had to be knocked-down to induce a stronger and statistically significant effect on apoptosis." (PMID 36497117, 2022). "This study aims to examine the expression of the homologues MAGOH and MAGOHB in melanocytes, several cutaneous melanoma cell lines and patient derived tissue samples and further elucidates the molecular function of both homologues in melanoma." (PMID 36497117, 2022). "To further investigate MAGOH/MAGOHB expression at the protein level and its significance for melanoma development we performed immunohistochemical analysis of patient derived human tissue samples of primary or metastasis derived cutaneous malignant melanomas." (PMID 36497117, 2022). "A simultaneous inhibition of MAGOH and MAGOHB could be an approach to trigger melanoma cells to cell death, possibly enhance effects of other therapies and reduce cancer progression." (PMID 36497117, 2022). "This could mean that, compared to other cancer types, cutaneous melanoma exhibits an increased sensitivity to MAGOH (and MAGOHB) depletion with regards to apoptosis, meaning that cutaneous malignant melanoma cells undergo apoptosis before the cell cycle is affected." (PMID 36497117, 2022). "Although PRDX6, MAGOHB, NUCKS1, DCAF13, and TXN genes as a panel displayed weak prediction of ICB response, the panel robustly stratified overall survival in patients with melanoma treated with anti-PD1 following progression on anti-CTLA4 therapy." (PMID 37835514, 2023). "Our findings demonstrate that cutaneous malignant melanoma cells rely on the expression of primarily MAGOH, but to an extent also MAGOHB, for their survival." (PMID 36497117, 2022). "To achieve an efficient, simultaneous KD of both homologues and to gain a sufficient effect on cutaneous malignant melanoma cells, we designed a Pool of siRNAs targeting both MAGOH and MAGOHB." (PMID 36497117, 2022). "In conclusion, simultaneous inhibition of MAGOH and MAGOHB expression substantially affects cell survival, indicating both MAGOH homologues as promising new targets for the treatment of melanoma." (PMID 36497117, 2022). "However, the molecular mechanisms of MAGOH in melanoma pathogenesis as well as the importance of MAGOHB in this process has so far not been investigated." (PMID 36497117, 2022). "Using functional assays, we could show that MAGOH, and not MAGOHB, is vital for melanoma cell growth, as an siRNA-mediated KD of only MAGOH significantly inhibits cell proliferation." (PMID 36497117, 2022).
brain tumors (2 papers, 2023 to 2024). "We investigated the roles of two EJC members, the paralogs MAGOH and MAGOHB, with respect to brain tumour development." (PMID 37294214, 2023).
cutaneous melanoma (2 papers, 2022 to 2024). A primary melanoma arising from atypical melanocytes in the skin. "In this study, analyzing the influence of MAGOH and MAGOHB on cell proliferation and apoptosis, we observed additive effects after a simultaneous depletion of both homologues in cutaneous melanoma cells." (PMID 36497117, 2022). "In order to assess if MAGOH and MAGOHB influence NMD activity in cutaneous melanoma, their expression was knocked-down in Mel Ho and 501Mel using the siMAGOH/B Pool and the cells were subsequently transfected with a NMD reporter plasmid." (PMID 36497117, 2022). "This study investigates the influence of MAGOH and its highly identical homologue MAGOHB with regards to cutaneous melanoma pathogenesis and cancer progression." (PMID 36497117, 2022). "This study revealed that cutaneous melanoma cells express significantly more MAGOH compared to MAGOHB on the mRNA as well as on the protein level." (PMID 36497117, 2022). "The previous results showed that a KD of MAGOH and MAGOHB dramatically induces apoptosis in cutaneous malignant melanoma cells." (PMID 36497117, 2022). "This indicates a significant influence of MAGOH and MAGOHB on the expression of the pro-apoptotic NMD target GADD45A in cutaneous malignant melanoma." (PMID 36497117, 2022). "The KD efficiency of the siPool on MAGOH and MAGOHB expression was confirmed in the cutaneous melanoma cell lines Mel Ho and 501Mel using qRT-PCR and Western blot analysis." (PMID 36497117, 2022). "To analyze the role of MAGOH and MAGOHB expression for tumorigenesis of cutaneous malignant melanoma, we examined RNA-sequencing (RNA-seq) data from “The Cancer Genome Atlas” (TCGA) regarding MAGOH and MAGOHB mRNA expression in cutaneous melanoma patients." (PMID 36497117, 2022). "This study identifies high MAGOH and MAGOHB protein expression in cutaneous melanoma cell lines and patient derived tissue samples." (PMID 36497117, 2022). "Our data indicate a critical role of MAGOH/MAGOHB expression for the tumor development of cutaneous malignant melanoma." (PMID 36497117, 2022). "In this study, we demonstrate that MAGOH and MAGOHB play an essential role in maintaining NMD activity in cutaneous melanoma." (PMID 36497117, 2022). "Our study demonstrates that the KD of MAGOH and MAGOHB increased GADD45A expression in cutaneous melanoma, an effect that might be mediated by an impairment of NMD induced by the loss of MAGOH and MAGOHB." (PMID 36497117, 2022). "Hence, the inhibition of MAGOH and MAGOHB could constitute a promising new approach for the treatment of cutaneous melanoma." (PMID 36497117, 2022). "In addition, it was further shown that a simultaneous downregulation of GADD45A together with MAGOH and MAGOHB could attenuate cell death in cutaneous melanoma cells, indicating GADD45A a strong tumor suppressor in cutaneous malignant melanoma." (PMID 36497117, 2022). "Investigating the molecular mechanisms behind the observed cell death after KD of MAGOH and MAGOHB, we revealed a significant influence on the mechanism of NMD in cutaneous melanoma." (PMID 36497117, 2022). "We identified that several cutaneous melanoma cell lines have an upregulated protein level of MAGOH and MAGOHB when compared to normal human epidermal melanocytes." (PMID 36497117, 2022). "As the KD of MAGOHB had proven to be efficient on the mRNA level, the absence of a KD of MAGOHB on the protein level supports the conclusion that MAGOH accounts for the majority of the total MAGOH and MAGOHB protein expression in cutaneous melanoma." (PMID 36497117, 2022). "In this study we could identify the NMD target GADD45A as strongly and significantly upregulated in cutaneous melanoma cells after KD of MAGOH and MAGOHB." (PMID 36497117, 2022). "The experiment showed that a KD of MAGOH/B did not lead to a shift to neither more exon skipping nor more exon inclusion in Mel Ho or 501Mel indicating that MAGOH and MAGOHB do not influence this kind of exon skipping in cutaneous melanoma." (PMID 36497117, 2022).
cutaneous melanoma (continued). "We further analyzed MAGOH and MAGOHB mRNA expression in different cutaneous melanoma cell lines derived from primary tumors (PT) or metastases (MET) using qRT-PCR and also observed a significantly higher expression of MAGOH compared to MAGOHB." (PMID 36497117, 2022). "A KD of MAGOH/MAGOHB and the resulting increase in GADD45A expression in cutaneous melanoma could possibly enhance the effect of other cancer therapies whose main mode of action is not to induce DNA damage, such as targeted therapy or immunotherapy." (PMID 36497117, 2022). "Together, the results revealed that cutaneous melanoma cells primarily rely on the expression of MAGOH, and not MAGOHB, for cell proliferation." (PMID 36497117, 2022). "After KD of MAGOH and MAGOHB using the siMAGOH/B Pool, a significant increase in GADD45A mRNA expression was observed in the cutaneous melanoma cell lines Mel Ho and 501Mel, whereas no obvious changes in the expression of GADD45B or GADD45G could be detected." (PMID 36497117, 2022).
glioblastoma (2 papers, 2023 to 2024). The most malignant astrocytic tumor (WHO grade IV). "High MAGOH/MAGOHB expression was observed in 14 tumour types; glioblastoma (GBM) showed the greatest difference compared to normal tissue." (PMID 37294214, 2023). "For example, the EJC proteins MAGOH and MAGOHB were among top hits identified in a functional genomic screening to identify RNA binding proteins with oncogenic potential in glioblastoma cells." (PMID 37294214, 2023). "Altogether, these results indicate that reduced expression of MAGOH/MAGOHB can create aberrant splicing events in glioblastoma cells, and suggest that high MAGOH/MAGOHB expression in tumours has an important role in preventing such events that are potentially harmful to tumour cells." (PMID 37294214, 2023). "We suggest that in these two scenarios (brain and glioblastoma development), highly proliferating cells demand efficient expression of cell cycle and division genes, and increased levels of MAGOH and MAGOHB are required to prevent defects in the splicing of these transcripts." (PMID 37294214, 2023).
gastric cancer (1 paper, 2022). A primary or metastatic malignant neoplasm involving the stomach. "In gastric cancer, both MAGOH and MAGOHB have been identified to regulate key pathological processes such as cell proliferation and cell cycle progression." (PMID 36497117, 2022). "Previous studies have identified that e.g., in gastric cancer, a depletion of MAGOH or MAGOH and MAGOHB, next to inducing apoptosis, also significantly inhibited cell cycle progression." (PMID 36497117, 2022).
glioma (1 paper, 2023). A benign or malignant brain and spinal cord tumor that arises from glial cells (astrocytes, oligodendrocytes, ependymal cells). "Increased MAGOH/MAGOHB expression was associated with poor prognosis in glioma patients, while knockdown of MAGOH/MAGOHB affected different cancer phenotypes." (PMID 37294214, 2023). "In gliomas, high levels of MAGOH/MAGOHB were associated with poor overall survival and worse response to treatments." (PMID 37294214, 2023). "Levels of MAGOH/MAGOHB expression were positively correlated with malignancy with 93.2% of grade 4 gliomas, 83.3% of grade 3 gliomas, but only 44.4% of grade 2 gliomas (p-value <0.001; displaying MAGOH/MAGOHB expression." (PMID 37294214, 2023). "Next, we investigated MAGOH and MAGOHB expression in 674 glioma samples (grade 4 samples, n = 161; grade 3 samples, n = 267; and grade 2 samples, n = 246)." (PMID 37294214, 2023). "MAGOH/MAGOHB expression was also evaluated by immunostaining in an independent glioma cohort from the Shanghai ChangZheng Hospital." (PMID 37294214, 2023). "Moreover, 61% (72/118) of grade 4 gliomas showed highly positive staining for MAGOH/MAGOHB expression, significantly more than in grade 2 (29.6%) and grade 3 (41.17%) gliomas (p-value = 0.005)." (PMID 37294214, 2023). "MAGOH/MAGOHB knockdown also affected viability of glioma stem cells (1919 and 3565)." (PMID 37294214, 2023). "High MAGOH/MAGOHB expression in grade 4 glioma seems to be particularly important, as loss of Chromosome 1p – where the MAGOH gene is located – is observed in some tumour types but rarely in grade 4 glioma." (PMID 37294214, 2023).
hearing-loss (1 paper, 2025). "The protein–protein interaction network analysis identified prominent interaction characteristics among neighboring genes of tinnitus-associated loci (RUNX2, TGFB2, CDH1, and DEFB family) and hearing-loss-associated loci (CDH1, PRR19, and MAGOHB)." (PMID 40362371, 2025).
non-small cell lung carcinoma (1 paper, 2023). A group of at least three distinct histological types of lung cancer, including non-small cell squamous cell carcinoma, adenocarcinoma, and large cell carcinoma. "To build on the specificity and relevance of MAGOH/MAGOHB impact on splicing, we analysed another dataset in which MAGOH/MAGOHB expression levels were modulated in ChagoK1, a cell line derived from a non-small cell lung cancer that contains an hemizygous MAGOH-deletion." (PMID 37294214, 2023).
viral infection (1 paper, 2021). "Interestingly, MAGOHB is targeted by has-miR-20a-5p, one of six miRNAs that previously have been reported to be antiviral in respiratory diseases, and were found to be downregulated in lung tissues during viral infection." (PMID 34070971, 2021).
cancer (6 papers, 2022 to 2023). A tumor composed of atypical neoplastic, often pleomorphic cells that invade other tissues. "Our analyses showed that MAGOH/MAGOHB display increased expression in the 14 cancer types analysed in relation to normal counterparts, suggesting a broad involvement in tumour development." (PMID 37294214, 2023). "MAGOH/MAGOHB were overexpressed (p-value <0.01, Wilcoxon rank sum test) in all analysed cancers compared to their normal counterparts." (PMID 37294214, 2023). "We investigated MAGOH and MAGOHB expression using datasets from GTex (Genotype-Tissue Expression and TCGA (The Cancer Genome Atlas)." (PMID 37294214, 2023). "Next, we investigated MAGOH and MAGOHB expression (here, considered MAGOH plus MAGOHB expression) in 5,715 tumour samples from 14 cancer types." (PMID 37294214, 2023). "MAGOH and MAGOHB as reciprocal paralog dependencies across cancer types suggest a rationale for targeting the MAGOHB-IPO13 axis in cancers." (PMID 35057823, 2022). "We next investigated whether high expression of MAGOH/MAGOHB is necessary to maintain cancer-relevant phenotypes." (PMID 37294214, 2023). "High expression of MAGOH and MAGOHB affect cancer-relevant phenotypes." (PMID 37294214, 2023). "Until now, the functional influence of MAGOH and MAGOHB in cancer has been essentially unexplored." (PMID 36497117, 2022). "However, MAGOH and MAGOHB are still poorly understood in the context of cancer." (PMID 37294214, 2023). "Consistent with this notion, the mouse homologous genes of human PRDX6, MAGOHB, NUCKS1, DCAF13, and TXN were upregulated by taxifolin in LL2 LC tumors and facilitated CTL-derived toxicity towards cancer cells." (PMID 37835514, 2023). "Therefore, considering the impact of MAGOH and MAGOHB on cancer phenotypes and the dissimilar sensitivity to their knockdown between GBM and differentiated neuronal cells, targeting EJC members such as MAGOH and MAGOHB may be an alternative therapeutic strategy to treat GBM." (PMID 37294214, 2023). "In addition, PRPF3 and MAGOHB have not been linked to cancer before." (PMID 35453681, 2022). "Additionally, the CNV condition and expression level of ASF1A, CDKN2A, MAGOHB, NADK, SPOP, and ARC were remarkably correlated in most cancer types." (PMID 37497116, 2023). "Similar results have previously been described for other types of cancer where both MAGOH and MAGOHB had to be depleted to gain a sufficient KD of MAGOH/MAGOHB protein levels to interrupt EJC function and to reduce tumor cell viability as well as Xenograft tumor growth in mice." (PMID 36497117, 2022). "Interestingly, NSF, SF3A3, PRPF3, and MAGOHB have never been studied in cancer." (PMID 35453681, 2022). "In this regard, PRDX6, MAGOHB, NUCKS1, DCAF13, and TXN displayed an overall negative correlation with multiple immune checkpoints in LUAD, LUSC, and other cancer types." (PMID 37835514, 2023).
tumor (6 papers, 2008 to 2023). "In the present study, we determined that MAGOH and MAGOHB are highly expressed in multiple tumour types." (PMID 37294214, 2023). "MAGOH and MAGOHB are aberrantly expressed in different tumour types while their knockdown affected the development of gastric cancer." (PMID 37294214, 2023). "MAGOH was strongly differentially expressed between tumor ER+ and TN subtypes, while MAGOHB was regulated by estrogen in MCF7 cells." (PMID 28263985, 2017). "This pathway can be activated in GC by overexpression of HRC (Histidine-rich calcium binding protein), upregulation of MAGOH and MAGOHB, and overexpression of YAP1 (Yes-associated protein 1), and subsequently promotes the tumour cell proliferation, migration, and invasion." (PMID 37037864, 2023). "Thus, we propose that in GBM cells, high MAGOH/MAGOHB expression would prevent aberrant splicing events that could ultimately compromise cell cycle and division, critical steps for tumour growth." (PMID 37294214, 2023). "PRDX6, MAGOHB, NUCKS1, DCAF13, and TXN displayed opposite trends on their potential facilitation of CTL function as well as correlations with immune checkpoints and TILs (tumor-infiltrating lymphocytes) compared to ITGAL, ITGAX, and TMEM119 in NSCLC." (PMID 37835514, 2023). "Also using our expression data, we identified several RNA processing factors that were differentially expressed between tumor subtypes and/or regulated by estrogen receptor, including YBX1, YBX2, MAGOH, MAGOHB, and PCBP2." (PMID 28263985, 2017).
MAGOHB also shares sentences with these, for which no sentence is quoted: metaphyseal chondrodysplasia (1 paper); respiratory diseases (1); retinitis pigmentosa (1); Tinnitus (1).